EPHA8 (EPH receptor A8)
Description:
Receptor tyrosine kinase which binds promiscuously GPI-anchored ephrin-A family ligands residing on adjacent cells, leading to contact-dependent bidirectional signaling into neighboring cells. The signaling pathway downstream of the receptor is referred to as forward signaling while the signaling pathway downstream of the ephrin ligand is referred to as reverse signaling. The GPI-anchored ephrin-A EFNA2, EFNA3, and EFNA5 are able to activate EPHA8 through phosphorylation. With EFNA5 may regulate integrin-mediated cell adhesion and migration on fibronectin substrate but also neurite outgrowth. During development of the nervous system also plays a role in axon guidance. Downstream effectors of the EPHA8 signaling pathway include FYN which promotes cell adhesion upon activation by EPHA8 and the MAP kinases in the stimulation of neurite outgrowth (By similarity).
Synonyms: EK3; hEK3; EEK
Tractability: Small molecule: an approved drug acts on it; a high-quality ligand is known; it belongs to a druggable protein family. Antibody: its Gene Ontology location is reachable by antibodies, with high confidence; UniProt places it where antibodies can reach, with medium confidence; UniProt predicts a signal peptide or a membrane-spanning region. PROTAC: UniProt records ubiquitination sites on it; a small molecule that binds it is known.
Target class: Tyrosine protein kinase Eph family; Protein Kinase; TK protein kinase group; Kinase; Enzyme
Gene: Protein-coding gene on chromosome 1 (22,563,489 to 22,603,595, forward strand). Ensembl gene ENSG00000070886.
Subcellular location: Cell membrane; Cell projection; Early endosome membrane
Pathways (Reactome):
Developmental Biology: EPH-Ephrin signaling; EPH-ephrin mediated repulsion of cells; EPHA-mediated growth cone collapse
Gene Ontology:
Molecular function: ephrin receptor activity; GPI-linked ephrin receptor activity; transmembrane-ephrin receptor activity; ATP binding; growth factor binding; protein kinase activity; protein tyrosine kinase activity; transmembrane receptor protein tyrosine kinase activity
Biological process: axon guidance; ephrin receptor signaling pathway; neuron projection development; neuron remodeling; positive regulation of MAPK cascade; positive regulation of phosphatidylinositol 3-kinase/protein kinase B signal transduction; regulation of cell adhesion; regulation of cell adhesion mediated by integrin; substrate-dependent cell migration; cell surface receptor protein tyrosine kinase signaling pathway; cell surface receptor signaling pathway
Cellular component: dendrite; neuron projection; plasma membrane; early endosome membrane; membrane
Genetic constraint (gnomAD): Loss-of-function variants: 58 observed, 100.61 expected, observed/expected ratio (o/e) 0.58, 90% interval 0.47 to 0.72. The upper end of that interval is the gene's LOEUF score, 0.72, which puts it in group 2 of 6, group 1 being the genes least tolerant of losing a copy. Missense variants: 1,304 observed, 1,420.3 expected, observed/expected ratio (o/e) 0.92, 90% interval 0.88 to 0.96. Synonymous variants: 559 observed, 580.61 expected, observed/expected ratio (o/e) 0.96, 90% interval 0.9 to 1.03.
Homologues: Orthologues: pig EPHA8 (98% identical), chimpanzee EPHA8 (97% identical), mouse Epha8 (95% identical), rat Epha8 (94% identical), guinea pig EPHA8 (94% identical), rabbit EPHA8 (94% identical), macaque EPHA8 (92% identical), dog EPHA8 (88% identical), tropical clawed frog epha8 (73% identical). Paralogues in human: EPHA5 (58% identical), EPHA4 (56% identical), EPHA7 (56% identical), EPHA3 (56% identical), EPHA6 (55% identical), EPHB1 (51% identical), EPHB2 (50% identical), EPHB3 (50% identical), EPHA2 (46% identical), EPHA10 (45% identical), EPHB4 (45% identical), EPHA1 (40% identical), and 41 more.
Diseases named in the same sentence as EPHA8 in open-access papers:
EPHA8 is named in the same sentence as 28 diseases in open-access papers, as found by Europe PMC text mining. Sharing a sentence is not in itself a finding about the gene and the disease. The quoted sentences say what the papers report.
glioma (7 papers, 2015 to 2023). A benign or malignant brain and spinal cord tumor that arises from glial cells (astrocytes, oligodendrocytes, ependymal cells). "In colon cancer and gliomas, EPHA8 has been reported to be targeted by miR-10a, resulting in the inhibition of cell invasion and migration." (PMID 37444464, 2023). "The lncRNA acts as an endogenous sponge for EphA8 by competing with miR-10a and increasing the levels of EphA8, which promotes apoptosis in glioma cells." (PMID 37891744, 2023). "Overexpression of EphA8 enhances the invasive ability of oral squamous cell carcinoma 34, miR-10a/EphA8 pathway can affect glioma invasion and migration through epithelial-mesenchymal transition." (PMID 32127941, 2020). "In glioma, downregulation of EphA8 by miR-10a induces epithelial mesenchymal transition (EMT) to promote tumor migration and invasion." (PMID 26989075, 2016). "Importantly, Bmi1 is known to regulate miRNAs, such as miR10a that has been shown to repress EphA8 in glioma cells, mediating the epithelial–mesenchymal transition and promoting cell migration and invasion." (PMID 31988455, 2020). "It has been shown that EphA8 is downregulated in colon cancer and glioblastoma, and EphA8 expression is downregulated by miR-10a to promote migration and invasion through EMT in glioma." (PMID 26989075, 2016).
breast carcinoma (4 papers, 2011 to 2024). "EphA8 acts as an oncogene and contributes to poor prognosis in gastric and breast cancer." (PMID 35770949, 2023). "In breast cancer, ART increased EPHA8, EPHA10, EFNA2 and reduced EPHA3, EPHA7, and EFNA3." (PMID 38630320, 2024).
colon cancer (3 papers, 2006 to 2023). "Downregulation of EphA8 has been detected in colon cancer as well as glioblastoma." (PMID 26989075, 2016). "For example, a dramatic 94-fold decrease in EPHA6 expression has been observed in colorectal tumors when compared to normal tissue, and EPHA8 expression has been detected only in colon tumor but not in corresponding normal tissue." (PMID 16740153, 2006).
gastric cancer (3 papers, 2022 to 2025). A primary or metastatic malignant neoplasm involving the stomach. "Erythropoietin-producing hepatocellular (Eph) receptor type A8 (EphA8) expression was associated with poor prognosis of patients with gastric cancer, and its knockdown decreased the expression of ADAM10, indicating that EphA8 is an upstream regulator of ADAM1052." (PMID 39755747, 2025). "For example, EphA1 and EphA4 are upregulated in gastric cancer; EphA2 overexpression in mammary epithelial cells induces tumorigenesis and EphA8 stimulates the proliferation, invasion, and migration of gastric cancer cells." (PMID 35681118, 2022). "While this gene has not been directly linked to Hippo, the related EphA2 receptor was shown to regulate YAP in breast and gastric cancer cells and other EPHA receptors (EPHA4, EPHA5, EPHA7 and EPHA8) emerged as Hippo pathway activators in an siRNA screen in HEK293T cells." (PMID 40869130, 2025).
glioblastoma (2 papers, 2016 to 2023). The most malignant astrocytic tumor (WHO grade IV). "Higher EphA2 and EphA8 expression were associated with poorer, while higher EphA3 expression was associated with better, prognosis in patients with glioblastoma, respectively." (PMID 37146061, 2023).
ovarian carcinoma (2 papers, 2016 to 2025). A malignant neoplasm originating from the surface ovarian epithelium. "EphA8 protein levels in cancer tissues were correlated with epithelial ovarian cancer (EOC) patients’ clinical characteristics and overall survival." (PMID 26989075, 2016). "EphA8 mRNA level was significantly higher in ovarian cancer tissues than in normal ovarian tissues or normal fallopian tube tissues." (PMID 26989075, 2016). "Similarly, EphA8 protein level was significantly higher in ovarian cancer tissues than in normal ovarian tissues, benign ovarian tumors and borderline tumors." (PMID 26989075, 2016). "EPHA8 is considered a negative prognostic factor for ovarian cancer patients." (PMID 41516312, 2025). "Finally, we did not provide the mechanistic insight of EphA8 in ovarian cancer development and progression." (PMID 26989075, 2016).
pancreatic cancer (2 papers, 2020). "The biochemical signaling networks linking EPHA8 and pancreatic cancer remain unclear; follow-up studies may provide useful insights into the role that EPHA8 plays in desmoplasia." (PMID 33233470, 2020). "Of these, only one examines EPHA8 in a pancreatic cancer context." (PMID 33233470, 2020). "Compared to other EPH kinase family members, EPHA8 is not as well studied in pancreatic cancer, and a query of PubMed using the search terms “EPHA8” and “pancreas” or “pancreatic” returns only two articles." (PMID 33233470, 2020).
benign ovarian tumors (1 paper, 2016). "We subsequently determined EphA8 protein expression in 223 archived ovarian tissue blocks, including 125 EOC tissues, 30 borderline ovarian tumor tissues, 30 benign ovarian tumor tissues, 20 normal fallopian tube tissues, and 18 normal ovarian tissues." (PMID 26989075, 2016).
breast tumors (1 paper, 2023). "Analogous to our observation that high EPHA1 expression in PCa was associated with worse patient survival, high EPHA8 expression in breast tumors has been associated with poor patient prognosis." (PMID 36806315, 2023).
keratinocyte carcinoma (1 paper, 2023). A skin cancer arising from the keratin-producing cells of the epidermis. "Using whole exome sequencing data, we performed groupwise tests for rare missense variants in our dataset and found robust associations (p < 10−6, Burden Zeggini test) between MC1R, EPHA8, EPO, MYCT1, ADGRG3, and MGME1 and keratinocyte cancer." (PMID 37444464, 2023).
leukemia (1 paper, 2025). A malignant (clonal) hematologic disorder, involving hematopoietic stem cells and characterized by the presence of primitive or atypical myeloid or lymphoid cells in the bone marrow and the blood. "Interestingly, the SASH1-Sam1 Y652A mutation inhibits the formation of the SASH1-Sam1/EphA8-Sam complex, whereas the leukemia-linked mutation G978D in EphA8-Sam highly reduces the binding affinity for SASH1-Sam1 by interfering with the network of interactions engaging the key G978 residue." (PMID 39942820, 2025).
medulloblastoma (1 paper, 2025). A malignant, invasive embryonal neoplasm arising from the cerebellum. "Multiple studies have linked EphA8 expression to medulloblastoma subtypes associated with neuronal migration pathways and poor prognosis." (PMID 41200151, 2025). "EphA8 is significantly overexpressed in primary medulloblastoma tissues compared to normal cerebellum, suggesting a role in tumor-specific biology." (PMID 41200151, 2025).
metastatic disease (1 paper, 2025). "Finally, we identified the EPHs (EPHA2, EPHA4, EPHA8, and EPHB4) and EFNs (EFNA1, EFNA3, EFNA4, and EFNB2) that are significantly overexpressed in the aggressive epithelioid histological subtype and revealed that the majority of EPHs/EFNs are overexpressed in metastatic disease." (PMID 41516312, 2025).
myocardial infarction (1 paper, 2020). Gross necrosis of the myocardium, as a result of interruption of the blood supply to the area, as in coronary thrombosis. "In addition, the EPH receptor genes EPHA2, EPHA8, and EPHB2 are located on chromosome 1 within region 1p34‐36, which has been identified as a locus for myocardial infarction by a genome wide search for susceptibility genes for myocardial infarction." (PMID 32337793, 2020).
prostate carcinoma (1 paper, 2018). A carcinoma that arises from epithelial cells of the prostate gland. "While EphA1 abundance was decreased in prostate cancer cell lines, EphA2, EphA5, EphA6, EphA7, EphA8, and EphA10 levels were elevated in some of the prostate cancer cell lines as compared to the normal prostate cell line." (PMID 29682554, 2018).
cancer (5 papers, 2016 to 2024). A tumor composed of atypical neoplastic, often pleomorphic cells that invade other tissues. "The results emphasize the marked elevation in expression for the majority of EphA genes among cancer patients, except for EphA5, EphA6, and EphA8." (PMID 38952552, 2024). "EPHA8 belongs to the erythropoietin-producing hepatocellular receptor family of transmembrane receptor tyrosine kinases, which are dysregulated in various cancers." (PMID 37444464, 2023). "Previous investigations of EPHA8 in normal cells and tumor cells from other cancer models suggest EPHA8 likely demonstrates kinase-dependent and kinase-independent oncogenic properties." (PMID 33233470, 2020). "The current study is the first to demonstrate EphA8's involvement in EOC and the first to show EphA8 is upregulated in cancer." (PMID 26989075, 2016).
tumor (5 papers, 2016 to 2025). "In addition, EphA8 was considered to be an independent prognostic factor in the advanced stage of this tumor." (PMID 40421081, 2025). "In previous studies, miR-10a inhibited epithelial-to-mesenchymal transformation (EMT), apoptosis and autophagy, induced chemo-resistance, invasion, proliferation, and tumor growth thought suppressing different protein such as EphA8, BCL2L11, TFAP2C, CDKN1A, p21, and p16." (PMID 27270310, 2016). "At last, the protein level of EphA8 was measured in primary GBM, relapsed GBM tissues, and non-tumor tissues via immunohistochemistry." (PMID 27270310, 2016). "In vitro experiments corroborated these findings, demonstrating that EphA8 overexpression potentially accelerates OSCC progression by augmenting tumor cell invasion, rather than proliferation capacity when using SCC-25 and H357 cancer cells." (PMID 40421081, 2025). "EphA8 overexpression potentially accelerates OSCC progression by augmenting tumor cell invasion, rather than proliferation capacity." (PMID 40421081, 2025). "Thus, ephrin-A5 could have been investigated as a potential tumor-suppressing ligand through the interaction with its tumor promoting receptors such as EPHA2, EPHA3, EPHA4, EPHA5, EPHA7, EPHA8, and EPHB2 in sarcomas." (PMID 35563562, 2022).
EPHA8 also shares sentences with these, for which no sentence is quoted: atherosclerosis (2 papers); colorectal cancer (1); colorectal tumors (1); esophageal cancer (1); ischemic cardiomyopathy (1); lymph node metastasis (1); melanoma (1); neurodegenerative disease (1); oral squamous cell carcinoma (1); renal clear cell carcinoma (1); spina bifida (1).